CD44 (CD44 molecule (IN blood group))
Diseases named in the same sentence as CD44 in open-access papers (continued):
Sharing a sentence is not in itself a finding about the gene and the disease.
breast carcinoma (continued). "Using flow cytometry assays, we found that 86.1% of MDA-MB-231 and 92% of Hs-578t breast cancer cells showed the CD44+/CD24− immunophenotype representative of cancer stem-like cells (CSCs)." (PMID 38392969, 2024). "Subsequent studies have sought similar CSCs in various solid tumors, such as CD44+CD24− cells in breast cancer, referred to as ‘primary CSCs’ (pri-CSCs)." (PMID 39184916, 2024). "Studies suggest the presence of a subpopulation of cells with stem cell-like properties within breast cancer, identified using stem cell markers CD44+/CD24-." (PMID 39239559, 2024). "Studies indicate CD44 as a shared marker for cancer stem cells in breast cancer, with high CD44 expression correlating with adverse BC prognosis, consistent with our findings." (PMID 38982317, 2024). "Using siRNA-CD44-EV (siRNA against CD44), MCF-7 breast cancer cells secreted CD44-positive EVs elicited by doxorubicin and carried proteins that confer drug resistance to breast cancer cells." (PMID 39273689, 2024). "In this study, we evaluated the correlation between the expression of CD44, CD63 and clinicopathological features, including the level of TIL and PIK3CA mutations, as well as survival in a Peruvian breast cancer series." (PMID 39430073, 2024). "Mesenchymal-like CSC (M-CSC) subtype has been established in breast cancer: mesenchymal-like CSCs are highly invasive, and express high levels of CD44 cell surface marker but low levels of CD24 marker (CD44high/CD24low)." (PMID 39546568, 2024). "In luminal-type breast cancer, CSCs are identified by specific surface markers, such as CD44+/CD24−/low cells." (PMID 38920716, 2024). "These cells possessed an EPCAM + ESA + CD44 + CD24−/low phenotype that was capable of propagating mammary tumors after low-dose injections into immunodeficient mice." (PMID 39547513, 2024). "As CD44 was upregulated by prolactin, blocking CD44 in mammary cancer cells would therefore inhibit iron transport, mediated through the CD44." (PMID 39201626, 2024). "Taken together, the observed accumulation of iron in mammary cancer cells by prolactin stimulation was at least partly mediated through the upregulation of CD44, which transported hyaluronate-Fe." (PMID 39201626, 2024). "A live cell CD44 antibody with green fluorophore conjugation was added to identify CD44 expression in mammary cancer cells." (PMID 39201626, 2024). "The same upregulation of CD44 by prolactin stimulation was also reproduced with another mouse mammary cancer cell line, Py230." (PMID 39201626, 2024). "The fusion of breast cancer cells with mesenchymal stem/stromal cells primarily produced CD44+/CD24−/low hybrid cells with variable ALDH positivity." (PMID 39547513, 2024). "To explore the correlation between EGFR and CD44, we evaluated the prognostic value of these proteins on overall survival according to mRNA expression levels in breast cancer patients." (PMID 37924112, 2023). "In breast cancer TGFB-RII expression is inversely correlated with ER expression and the CD44+/CD24- cell phenotype has been associated with ER-/TGFB-RII+ patients." (PMID 36831452, 2023). "Its efficiency was tested against CD44+ breast cancer cells (4T1) in both the in vitro and in vivo systems, as well as in CD44 normal fibroblast cells (NIH-3T3)." (PMID 36986774, 2023). "A positive association between the levels of expression of MLLT11 and CD44, an adhesion molecule and direct target of the WNT/beta-catenin signaling, has been reported in breast cancer." (PMID 38203610, 2023). "In head and neck, and breast cancer, it has been reported that the radioresistance induced by GDF15 is linked to the expression of stemness markers (CD44, Sox2, and Nanog) and the ability of cancer cells to form spheroids." (PMID 38201456, 2023). "A possible illustration of this mechanism is found in the behavior of a particular subset of isolated breast cancer CTCs expressing CD44." (PMID 37492150, 2023).
breast carcinoma (continued). "CD44 mRNA expression was induced following chronic exposure to 300 μM DETANO and is consistent with induced expression in high NOS2 expressing ER- breast tumors and NO-induced CD44 protein expression in TNBC breast cancer cells." (PMID 36830680, 2023). "Specifically, we employed CD44 antibody conjugates (bearing a maleimide group) that are specific to the CTCs of breast cancer to thiol-Sepharose beads 6B." (PMID 37509107, 2023). "Although comparable effects have been reported in other cancer patients, it has been revealed that therapy successfully lowered circulating anti‐CD44 antibody levels in breast cancer patients." (PMID 36289579, 2023). "Several studies demonstrated that CD44 is a potential therapeutic target among various malignant entities, e.g., triple-negative basal-like breast cancer, squamous cell carcinomas, and acute myelogenous leukemia." (PMID 38106992, 2023). "PRG4 suppresses TGFβ-induced invasiveness of breast cancer cells by inhibiting the cell surface cluster of differentiation 44 (CD44) signaling." (PMID 37621676, 2023). "The JAK2/STAT3 signaling pathway is required for growth of CD44(+) CD24(−) stem cell-like breast cancer cells, particularly in basal-like breast cancers and is independently associated with breast cancer metastasis and poor prognosis." (PMID 36635351, 2023). "Recent studies have confirmed CD44 + /CD24- phenotype in breast cancer patients was negatively correlated with postoperative DFS and OS." (PMID 36964570, 2023). "The CD44/CD104 expression marker analysis revealed that most of the HS578T-Hyg breast cancer cells were CD44+/CD104-, which is further in agreement with a M state." (PMID 38139138, 2023). "Reflecting these results, when we checked the CSC contents of different breast cancer cell lines, we obtained higher percent of (CD44+/CD24−) CSCs in TNBC cell lines, i.e., MDA-MB-468 and MDA-MB-231, as compared to luminal MCF-7 cell line." (PMID 38038865, 2023). "CSCs derived from breast cancer cells with CD44+/CD24 low/− phenotype have the ability of heterogeneous differentiation, initiating diverse tumors and forming mammospheres." (PMID 36835085, 2023). "Isolated breast cancer cells with CD44+/CD24− profile are able to form mammospheres in vitro and xenografts in mice model in vivo." (PMID 37492743, 2023). "In another study, active targeting of CD44 expression in breast cancer by doxorubicin and cisplatin co-loaded chitosan-HA nanoparticles provided significant anticancer activity." (PMID 37283735, 2023). "Triple-negative breast cancer (TNBC) displays the breast cancer stem cell (BCSC) phenotype of CD44+/CD24-, possesses tumor-initiating properties, and is associated with stem cell-like characteristics in breast cancer." (PMID 37736551, 2023). "Although several studies have reported differential α2,3-sialylation in metastatic breast cancer, few glycoproteins including CD44 and mucins have been identified to be responsible for this observation." (PMID 37942010, 2023). "MCF-7 breast cancer cell-derived exosomes loaded with siRNA were used against CD44 in breast cancer cells." (PMID 36678782, 2023). "CD44+/CD24− breast cancer cells have also been shown to upregulate NF-κB compared to CD44−/CD24+ breast cancer cells." (PMID 37370720, 2023). "In the current study, we designed a recombinant protein that included the variable component of the CD44 (CD44v) extracellular domain to apply in clinical diagnosis of breast cancer." (PMID 36289579, 2023). "Further investigation is required to confirm this observation, but it opens intriguing opportunities for further use of dragmacidin D to study the duality of CD44 in breast cancer." (PMID 38132962, 2023). "Following the therapy, the circulating anti‐CD44 IgG in breast cancer patients was depleted in proportion to the period before treatment." (PMID 36289579, 2023).
breast carcinoma (continued). "CD44, which is often used as a biomarker for breast cancer stem cells, was significantly differentially expressed between the cancer cells and epithelial cells and between the cancer cells and redirected cells." (PMID 36765535, 2023). "MiR-146a was found to be up-regulated in CD44+CD24− BCSCs from human breast cancer samples and in cisplatin-resistant MCF-7 cells." (PMID 37374142, 2023). "In a breast cancer model, HA (Hyaluronic Acid)-SPIONs coupled with anti-CD44 (Cluster of Differentiation 44) antibodies have been studied." (PMID 37650011, 2023). "Previously, we have shown the immunomodulatory effect of cisplatin in triple negative murine breast cancer model reducing the emergence of splenic CD44+, IL-17A+ myeloid suppressor cells." (PMID 37901220, 2023). "In MCF-7 breast cancer cells, Twist markedly elevates the expression levels of CD44 via activation of the β-catenin and Akt pathways." (PMID 37835592, 2023). "EMT, chemoresistance, and invasion ability are enhanced by NO signaling upregulating the stem cell marker CD44 and other basal-like breast cancer-specific proteins." (PMID 37108109, 2023). "MeCSC subpopulations such as CD44v6 CSCs or CD26+ CSCs in colorectal cancer, CD44+ CSCs in breast cancer, and CXCR4+ CSCs in prostate cancer have also been found." (PMID 37370081, 2023). "Immunohistochemical analysis of 125 breast cancer patients disclosed that the amount of CD44 protein correlates positively with poor disease-free survival and overall survival (OS)." (PMID 37835592, 2023). "Kumar and co-workers developed an electrochemical biosensor to detect CD44 in breast cancer based on graphene quantum dots." (PMID 37754116, 2023). "Iron oxide nanoparticles can increase labile iron pool-induced ferroptosis in chemoresistant breast cancer cells for therapeutic purposes through CD44-mediated endocytosis." (PMID 37715221, 2023). "In this study, HA-coated AM nanoparticles were developed and applied to actively target MCF-7 breast cancer cells that express CD44." (PMID 36850308, 2023). "CD44 expression on breast cancer cell surface is increased compared to normal breast epithelial cells." (PMID 38188613, 2023). "These include MUC1 and CD44 for breast cancer, CD44 for colon cancer, or CD34 for leukemia, although one cell is not restricted to only one carrier." (PMID 37915564, 2023). "successfully developed liposomes that carry anti‐CD44 antibodies and anti‐IL6R antibodies that specifically target the TME of CD44+ breast cancer cells, thereby inhibiting metastasis in breast cancer mouse models." (PMID 37560754, 2023). "CD44, a surface biomarker extracted from CICs, is among the most effective biomarkers for the early identification of breast cancer." (PMID 36289579, 2023). "The known CSC markers include CD44 + CD24- in breast cancer, CD44 + and CD133 + in colon and gastric cancer, CD34 + CD38- in leukemia, and CD133 + in glioblastoma and sarcoma." (PMID 36864434, 2023). "Chemotherapeutic drugs led to cancer stem cell (ALDH+/CD44+) abundance in breast cancer, which was abrogated by belinostat exposure." (PMID 36969235, 2023). "For example, it was demonstrated that the secretion of interleukin (IL)-6 from CD44+/CD24low/− breast cancer cells is dependent on autophagy and necessary for CSC maintenance." (PMID 36902427, 2023). "CSCs have been identified in breast cancer by different markers (primarily being CD44+/CD24low/−), and by their ability to generate a heterogenous cell population, resist chemotherapy and express an epithelial-to-mesenchymal (EMT) phenotype." (PMID 37190183, 2023). "Xenografts obtained from the TRIM28KD MDA-MB-231 breast cancer cell line (that contains an enriched CD44+/CD24−/low subpopulation) exhibited reduced tumor formation." (PMID 37492743, 2023).
breast carcinoma (continued). "HAS2 and CD44 are known to be highly expressed in ER− breast cancer, promoting tumor aggressiveness." (PMID 37568628, 2023). "Microarray analysis of breast cancer tumors showed that the gene expression profile of the CD44+/CD24– fraction resembled that of stem cell–like cells, and this subpopulation was able to form mammospheres in vitro." (PMID 37377604, 2023). "A Ru(II) triazine complex has been reported to eliminate CSCs in CRC HCT-116 CD44+ and breast cancer MCF-7 CD44+ cells." (PMID 38104089, 2023). "The important exon v10—one of the isoforms of the 20-exon CD44 single gene—plays a critical role in promoting the progression and metastasis of breast cancer." (PMID 37175137, 2023). "Breast cancer stem-like cells (BCSLCs) were isolated by sorting CD44+CD24- cells from suspension cultured breast cancer (BC) spheroids." (PMID 36923432, 2023). "In breast cancer, the CD44+/CD24- stem cell population was significantly increased in cancer cells induced by radiotherapy." (PMID 37213675, 2023). "The CD24−/CD44+ phenotype in the cell population is commonly used to characterize CSCs in breast cancer." (PMID 37370134, 2023). "CD44 (possibly CD44v) has important biological activities for CICs, and there is a link between incremental CD44 isoform regulation and tumor development to the metastatic phase and breast cancer recurrence." (PMID 36289579, 2023). "For breast cancer cases, the CD44 high/CD24 low phenotype exacerbates aggressiveness, accelerates antitumor drug resistance and facilitates tumor progression." (PMID 37353799, 2023). "For example, high expression of CD44, like RHAMM, is linked to breast cancer initiation yet both proteins can perform metastasis suppressor functions in experimental models of breast cancer susceptibility." (PMID 37349798, 2023). "The stem-cell markers CD44+/CD24− have been reported in various breast cancer subtypes and histological stages." (PMID 37237509, 2023). "CD44 is frequently shed into the extracellular milieu, and serum levels of CD44 have been proposed as a prognostic marker in breast cancer." (PMID 36768435, 2023). "In this research, we performed immunohistochemical (IHC) staining on sixty breast cancer surgical specimens for c-Myc, CD44, CD24, CD133 and ALDH1A1." (PMID 37353799, 2023). "In another study, it was shown that inhibition of autophagy by knockdown of ATG7 or BECN1 modified the CD44+/CD24low/- (stem cell phenotype) population of breast cancer cells by regulating CD24 and IL-6 secretion." (PMID 37886168, 2023). "The micelle-mediated delivery increased the cytotoxicity of DOX on the CD44+ breast cancer cells (MCF-7) by six times compared with the application of free DOX solution." (PMID 37720349, 2023). "Intriguingly, isoforms of CD44 can be found among a variety of breast cancer cell populations and correlated with different levels of cancer cell tumorigenicity." (PMID 36768445, 2023). "Human stem cells with the surface marker phenotype Lin-CD10-CD24-PROCR+CD44+ were identified in normal mammary epithelium and breast carcinomas." (PMID 36632469, 2023). "It has been previously reported that CD44 can promote CSC traits of metastatic breast cancers by activating the PDGFRβ/Stat3 signaling pathway." (PMID 37117249, 2023). "first reported breast cancer stem cells (BCSCs) with specific markers (EpCAM/CD44+/CD24-/low) capable of initiating tumorigenesis in vivo." (PMID 37324011, 2023). "HA is a natural polysaccharide made up of D-glucuronic acid and N-acetyl-D-glucosamine, which shows a high affinity for the integral membrane glycoprotein cluster differentiation-44 (CD44) on the cell surface in breast cancer." (PMID 36850308, 2023).
breast carcinoma (continued). "The nanoparticles additionally have been coated with hyaluronic acid (HA) for better cellular uptake by CD44-overexpressed 4T1 breast cancer cells via an active targeting mechanism." (PMID 38067351, 2023). "A pioneering study indicated that CD44 + /CD24- cells can be recognized as prospective breast cancer stem cells." (PMID 37919766, 2023). "Some research has shown that CD133 and CD44 are used as markers to identify cancer stem cells in diverse cancers like breast carcinoma." (PMID 37009003, 2023). "A previous study has reported that hyaluronan (HA)-induced promotion of CD44 signaling potentiated the invasive process of breast cancer cells through regulating the expression of uPA." (PMID 37842093, 2023). "CD44 is a hyaluronan receptor known to increase the efficiency of distant metastasis of breast cancer." (PMID 37492150, 2023). "M-Sal presented significantly higher activity than free Sal to reduce the cell population with the CD44+/CD24– phenotype on the breast cancer cells (MCF-7) and the mouse tumor model." (PMID 37720349, 2023). "Firstly, CD44‐positive (CD44+) breast cancer cells are enriched by anti‐CD‐functionalized magnetic beads (MB‐CD44)." (PMID 40626205, 2023). "KHDRBS3 is upregulated by SALL4 as a splicing factor for CD44, which enhances stemness in breast cancer cells." (PMID 37848941, 2023). "The CAT/THA-Ce6-sAu-NRs were able to easily accumulate in CD44-overexpressing MDR breast cancer cells via CD44-HA recognition." (PMID 37376161, 2023). "CSC with high expression of CD44 are also considered a poor prognostic indicator in different types of tissues such as colorectal cancer, breast cancer, and ovarian cancer tissues." (PMID 36604635, 2023). "Recent studies reported that the activation of Notch signaling is necessary for maintenance of CD44+/CD24−/low tumor-initiating cells in breast cancer." (PMID 37919766, 2023). "Breast cancer cells expressing the phenotypic CD24−/CD44+ markers on their surface have stem cell-like properties, including the ability to self-renew and initiate tumors." (PMID 37370134, 2023). "Breast cancer with lymph node metastases were in general associated with lower levels of the CSC genes ALDH1A3 and CD44, pluripotency markers POU5F1 and NEAT1, EMT marker SLUG, and drug resistance associated gene ERBB2, after DOX treatment." (PMID 38124067, 2023). "Hyaluronic acid was functionalized on the exterior surface of the nanocomposite as a targeting moiety for CD44 to improve the cellular internalization and specificity for breast cancer cells." (PMID 37765168, 2023). "The overexpression of Slug in MCF-10A and MCF-7 breast cancer cells (CD44-/CD24+) generates a subpopulation of cancer stem cells with a CD44+/CD24+ phenotype showing an enhanced mammosphere-forming ability." (PMID 37835592, 2023). "Accordingly, it was shown that tumor suppressor Rb represses CD44 dependent collective invasion, release of breast cancer cells in circulation and lung metastasis." (PMID 37006265, 2023). "Further, PD-L1 knockdown in breast cancer cells downregulated the expression of CD44 and upregulated the expression of CD24, suggesting that PD-L1 expression positively regulates stem-like cells activity in the cancer tissues." (PMID 36604635, 2023). "To determine the expression status of the C1ql4 gene in breast cancer stem cells, we isolated CD44+CD24- cell populations from MCF-7 cell lines by flow cytometry." (PMID 37324011, 2023). "We first investigated the expression of the oncoprotein c-Myc and four breast cancer stem cell (BCSC) biomarkers: CD44, CD24, CD133 and ALDH1A1." (PMID 37353799, 2023). "In the current study, we detected the CD44+/CD24- subpopulation cells from breast cancer cells, and confirmed that miR-1275 plays a pivotal role in decreasing chemoresistance by reducing the properties of CSCs." (PMID 36594100, 2023). "CD44+ CD24− cells are more tumorigenic in breast cancer due to their higher invasion and migration ability." (PMID 37529165, 2023).